INS (insulin)
Diseases named in the same sentence as INS in open-access papers (continued):
Sharing a sentence is not in itself a finding about the gene and the disease.
Insulin resistance (continued). "This study describes a head to head comparison of the two most commonly utilized diet induced obesity models for the study of obesity and type 2 diabetes, with a focus on the increased insulin secretion in response to insulin resistance as the primary endpoint." (PMID 23201760, 2012). "As skeletal muscle is the major site of glucose disposal, myocyte production of cytokines with insulin desensitizing action could also contribute to the pathology of equine insulin resistance." (PMID 26486919, 2012). "However, insulin resistance occurs when a normal dose of insulin is incapable of eliciting these metabolic responses." (PMID 22761194, 2012). "Elevated insulin and glucose concentrations are direct consequences of insulin resistance." (PMID 23300589, 2012). "The inflammatory markers originate from both adipocytes and inflammatory macrophages infiltrating the expanding adipose tissue, and induce pro-inflammatory transcription factors which interfere with the systemic actions of insulin, resulting in peripheral insulin resistance." (PMID 23049932, 2012). "In individuals with insulin resistance, the situation is aggravated by increased circulating insulin levels, which stimulate the synthesis of triglycerides and increases the secretion of VLDL cholesterol, contributing to a greater accumulation of fat in the liver." (PMID 22221448, 2012). "Sirt1 activation with resveratrol protected mice fed a high-fat diet against metabolic disease and insulin resistance, and treatment of adipocytes with Sirt1 activators increased glucose uptake and insulin sensitivity while Sirt1 knock down exerted the opposite effects." (PMID 22822451, 2012). "Since these two components are key components in the upstream of insulin signaling pathway, such impairment may lead to insulin resistance." (PMID 22721429, 2012). "Therefore, preventing insulin resistance and potentiating β-cell function and mass is even more important for preventing type 2 diabetes in East Asians, since they have little excess insulin secretory capacity to buffer the effects of insulin resistance." (PMID 23270397, 2012). "The SOCS3 connection between IL-6 and insulin signaling could be an explanation to the observation that mice, when infused with high doses of IL-6 (0.5 μg/h), induced insulin resistance in skeletal muscle." (PMID 22761857, 2012). "Insulin resistance is defined as an inadequate response by insulin target tissues, such as skeletal muscle, liver, and adipose tissue, to the physiologic effects of circulating insulin." (PMID 22804097, 2012). "Insulin resistance can descend the repression of insulin on the concentrations of plasma free fatty acids, increase the plasma levels of free fatty acids, promote free fatty acids into the liver, and stimulate the synthesis and release of very low density lipoprotein (VLDL) in the liver." (PMID 23039238, 2012). "Further, the low level of insulin secretion or high insulin resistance was suggested to divert more energy to the insulin-independent tissues (brain and red blood cells) and less to the insulin-dependent tissues (skeletal muscles, liver, fat cells, and abdominal viscera)." (PMID 23133645, 2012). "Thus, insulin release by human beta cells can be increased by about four- to fivefold and beta cell mass enhanced by about 50% during insulin resistance." (PMID 22460761, 2012). "Patients in the high insulin resistance group had higher mean disease activity (P = 0.011), fasting serum insulin (P < 0.001), plasma glucose (P < 0.001), triglycerides (P = 0.015), and systolic blood pressure levels (P = 0.024) than patients with low insulin resistance." (PMID 22691241, 2012). "Insulin resistance (IR) was considered as HOMA index (insulin × fasting glucose/22.5) ≥ 2.77." (PMID 22356810, 2012).
Insulin resistance (continued). "Insulin can directly suppress GH secretion from the pituitary, while more severe insulin resistance may impair GHRH and the arginine-induced GH response in NAFLD patients." (PMID 22952901, 2012). "There has been growing interest in identifying genes and processes that could trigger insulin resistance beyond defects on the insulin signaling cascade itself." (PMID 23236286, 2012). "One could speculate that a sustained hyperinsulinism, stimulated by insulin and enhanced by insulin resistance, could impair the balance between PI3K/Akt and MEK/ERK signaling." (PMID 23112573, 2012). "A major mechanisms that has been implicated in the development of endothelial dysfunction in the metabolic syndrome at peripheral vessels is insulin resistance itself, since insulin, via Akt, stimulates endothelial NO release through a Ca2+ independent pathway." (PMID 22509248, 2012). "High levels of insulin cause fatty liver in insulin resistant states, suggesting that mice with type 2 diabetes manifest selective hepatic insulin resistance: insulin fails to suppress gluconeogenesis but continues to activate lipogenesis." (PMID 23028442, 2012). "In addition, insulin resistance seems to modify the effect of insulin on the vascular wall; anti-atherogenic in the insulin sensitive state and pro-atherogenic in the insulin resistant state." (PMID 23300589, 2012). "As a result, MSKO mice on high fat (HF) diets exhibited impaired insulin signaling in skeletal muscle, fat, and liver, and developed systemic insulin resistance in glucose tolerance tests, insulin tolerance tests, and hyperinsulinemic-euglycemic clamp experiments." (PMID 23183898, 2012). "Furthermore, insulin resistance measured at 24 h post-LPS was preceded by specific modulation of adipose inflammatory and insulin signaling pathways." (PMID 22989045, 2012). "The results of this randomised clinical trial demonstrated that in forty-two diabetic participants, BVFE produced significant decrease in TG, TC, LDL-c, apoB, insulin resistance, glucose, insulin and significant increase in TAC compared to the placebo group at the end of study." (PMID 24250489, 2012). "Thus, the attenuation of insulin resistance and potentiation of insulin secretion are required to prevent type 2 diabetes." (PMID 22550941, 2012). "In individuals who are at risk for developing type 2 diabetes, the DI may be reduced due to inadequate compensatory insulin secretion for a given degree of insulin resistance." (PMID 23015803, 2012). "Hyperlipidemia, free fatty acids (FFAs) overload and lipid accumulation in non-adipose tissues influence both insulin action and insulin secretion and are frequently associated with insulin resistance and the development of T2DM." (PMID 23150952, 2012). "Despite similar weight gain, several sex differences were detected since male but not female mice developed visceral inflammation, glucose intolerance, insulin resistance, and hyperinsulinemia, as well as subsequent adaptations at the level of the insulin-producing islets." (PMID 23049932, 2012). "Therefore, it is plausible that development of insulin resistance in the liver and in the skeletal muscle and concomitant weakening of insulin secretion will result in progressive elevation of 1-hour glucose concentration, as suggested by our results." (PMID 22567007, 2012). "This insulin resistance results from decreased insulin sensitivity in tissues." (PMID 22942720, 2012). "This suggests the possibility that insulin hypersecretion may precede and drive the early stages of insulin resistance." (PMID 22272304, 2012). "Moreover, timeline studies performed in rodents have shown that whilst hepatic insulin resistance is observed within 3 days of high fat diet, this is followed by insulin resistance in muscle only at 3 weeks." (PMID 22586466, 2012). "Thus, anti-TNF-α treatment ablates insulin resistance, thereby normalizing the response of host tissues to insulin." (PMID 22606220, 2012).
Insulin resistance (continued). "We speculate that the delay in glucose metabolic clearance in patients with insulin resistance induces greater attenuation of postprandial FMD in subjects with insulin resistance than in subjects with normal insulin sensitivity." (PMID 22891922, 2012). "In many obese individuals, insulin resistance is compensated by increased insulin production." (PMID 22143698, 2012). "Since insulin resistance was frequently associated with PCOS, insulin-sensitizing interventions might theoretically have beneficial effects on hsCRP levels." (PMID 23843832, 2012). "However, it must be noted that we previously published that oral administration of BPA at exactly the same doses used in the present work produced insulin resistance, as manifested by alteration of insulin tolerance test." (PMID 22470480, 2012). "All together, these data may indicate that the increased apelin levels that we observe in T2D patients could represent a compensatory mechanism to reduce both insulin resistance and impaired insulin-secretion." (PMID 23227256, 2012). "Mouse model studies revealed that obesity induced hypothalamic resistance to insulin may be involved in pathogenesis of peripheral insulin resistance; however, the exact role and mechanism of hypothalamus involvement in T2D is still not clear." (PMID 23028558, 2012). "Within the first week of high-fat feeding in mice, insulin resistance primes the islets to respond by becoming hyperplastic to meet the increased demands of insulin production to compensate for insulin resistance and thereby maintain normal blood glucose levels." (PMID 23326022, 2012). "Assessments included body mass index (BMI), insulin sensitivity (Homeostasis Model Assessment of insulin resistance, HOMA and the Quantitative Insulin sensitivity Check Index, QUICKI), and RA disease characteristics before and following six months of anti-TNFα treatment." (PMID 22765047, 2012). "Inflammation and insulin resistance are closely linked and inflammatory cytokines such as tumor necrosis factor (TNF), interleukin (IL)-6, IL-1 and IL-8 may inhibit insulin signaling by multiple mechanisms." (PMID 22691241, 2012). "Genetic variability of the major subunit (CACNA1E) of the voltage-dependent Ca2+ channel CaV2.3 is associated to risk of type 2 diabetes, insulin resistance and impaired insulin secretion in nondiabetic subjects." (PMID 22427875, 2012). "In conclusion, our results suggest a robust association between low serum amylase and BMI, as well as latent associations with decreased basal insulin and basal insulin secretion, and with insulin resistance in a nonlinear manner." (PMID 22748134, 2012). "Abnormalities in other hormones such as reduced secretion of the incretin glucagon-like peptide 1 (GLP-1), hyperglucagonemia, and raised concentrations of other counterregulatory hormones also contribute to insulin resistance, reduced insulin secretion, and hyperglycaemia in type 2 diabetes." (PMID 23316348, 2012). "Therefore, SOCS3 is a single molecule that mediates both leptin and insulin resistance due to its ability to down-regulate leptin and insulin signaling." (PMID 23115649, 2012). "Previous studies support this hypothesis of insulin resistance showing that subjects with low birth weight or slow early growth have decreased insulin sensitivity reflecting muscle and adipose tissue insulin resistance." (PMID 21904606, 2011). "At the end of 8 weeks, serum glucose, insulin, triglyceride and uric acid levels, as well as insulin resistance, as measured by glucose tolerance test, were significantly (p < 0.01) increased in fructose fed rats (Diabetic group) when compared to the cornstarch fed (Control) rats." (PMID 21794123, 2011). "Interestingly, under insulin resistance conditions we observed that insulin blunted the increase in NO generation induced by sildenafil." (PMID 21297971, 2011).
Insulin resistance (continued). "However, the product of the glucose AUC and insulin AUC, an indicator of insulin resistance, was significantly improved, i.e. reduced, in response to one year of DHEA replacement (~22%, p,0.01), and was unchanged in the placebo group." (PMID 21566261, 2011). "During insulin resistance, increased IL-6 might not only diminish insulin sensitivity by suppressing insulin signal transduction but also interfere with anti-inflammatory effect of insulin, and might favour inflammation during insulin resistance." (PMID 22144985, 2011). "On regression analyses, changes in BMI predicted changes in insulin (B = 4.9 ± 2, p = 0.03), insulin resistance (B = 1.75 ± 0.65, p = 0.02) and leptin (B = 2.2 ± 1, p = 0.046) but not on ghrelin (B = 38 ± 72, p = 0.61), adiponectin (B = -0.02 ± 1, p = 0.98) or resistin (B = -0.09 ± 0.25, p = 0.74)." (PMID 21676224, 2011). "In this context, insulin resistance may be considered a compensatory mechanism that protects the cells against further insulin-stimulated glucose and fatty acid uptake and, therefore, oxidative damage." (PMID 21276212, 2011). "Reducing the post-prandial spikes of glucose and insulin following a high GI meal may also reduce the risks of developing insulin resistance, which can lead to cardiovascular disease." (PMID 21414227, 2011). "Carriers of S319 do not develop MODY; rather in the context of obesity and insulin resistance, carriers appear to have a compromised ability to mount an insulin response, resulting in earlier loss of glycemic control." (PMID 21208426, 2011). "Ghrelin correlated with changes in insulin resistance, suggesting that other factors besides body weight may play a role in its regulation including changes in insulin sensitivity." (PMID 21676224, 2011). "Low triglyceride levels are usually associated with increased insulin sensitivity but it appears that the relationship between triglycerides and insulin sensitivity differs between races, African-Americans for example having lower triglyceride levels in spite of increased insulin resistance." (PMID 22112229, 2011). "We hypothesize that, in the early stages of insulin resistance, there are counter-regulatory systems to the trophic effects of insulin on α-cell proliferation." (PMID 21283589, 2011). "Molecular studies have demonstrated that MSG-obese animals have a decrease in signalling of their insulin-stimulated IRS/PI3K/Akt pathway in muscle and adipose tissue, which may be an important hallmark of insulin resistance of those animals." (PMID 21860615, 2011). "However, a defect at this first step in insulin action is often observed in conditions of in vivo insulin resistance." (PMID 22046423, 2011). "The offspring of SE mothers showed significant glucose intolerance, which may be an early manifestation of impaired brain insulin signaling that could lead to a profound insulin resistance and type 2 diabetes later in life." (PMID 22076142, 2011). "Nevertheless, rs738409 has been shown not to be associated with insulin resistance although a previous study demonstrated an association with insulin secretion in response to oral glucose tolerance test." (PMID 21533024, 2011). "Insulin resistance was measured using the short insulin tolerance test." (PMID 22254118, 2011). "Individuals with IFG mainly had hepatic insulin resistance and normal muscle insulin sensitivity, while individuals with IGT predominantly were characterized by moderate to severe muscle insulin resistance with normal to slightly reduced hepatic insulin sensitivity." (PMID 21556362, 2011). "Pioglitazone increased insulin sensitivity in part by activating kinase of the receptors through indirect effect on insulin receptors and that the drug may have useful benefits in insulin resistance of type 2 diabetes." (PMID 23554718, 2011). "Thus, diet-induced insulin resistance accelerates β-amyloid (Aβ) pathology, whilst peripheral insulin injection induces tau phosphorylation." (PMID 21347323, 2011).
Insulin resistance (continued). "We also observed that in the presence of Wortmannin, a biochemical inhibitor of phosphatidylinositol 3-kinase (a hallmark of insulin resistance), VCAM-1 expression was greater in the presence of TNFα plus insulin as compared to that seen with insulin or TNFα alone." (PMID 22093181, 2011). "It is known to impair insulin signaling, leading eventually to insulin resistance." (PMID 22013536, 2011). "Adiponectin has been hypothesized to act as a link between accumulated fat mass and altered insulin sensitivity even though the contribution to the development of insulin resistance is complex and not fully understood." (PMID 21760816, 2011). "Although insulin resistance has been induced by injecting myostatin into mice, this does not prove that the normal basal level of myostatin is a significant determinant of insulin sensitivity." (PMID 21390326, 2011). "Insulin levels were significantly higher in MetS patients, indicating insulin resistance." (PMID 22110764, 2011). "As BCAAs are under the influence of circulating insulin, the insulin resistance state of cirrhosis may limit there nutritional benefit unless systemic insulin replacement is implemented." (PMID 21994873, 2011). "In sc and om cells in this study, the incremental response to insulin stimulation was similar with and without low dose Dex and suggests that this dose (5 nM) is not sufficient to cause insulin resistance." (PMID 22022575, 2011). "Hence, reduced adiponectin contributes to insulin resistance as this adipokine, an anti-inflammatory agent, has been shown to enhance insulin sensitivity." (PMID 22144985, 2011). "Indeed, co-silencing both PKC isoforms relieved insulin resistance, by preventing the drop in insulin stimulated GLUT4myc translocation and glucose uptake caused by CM-PA." (PMID 22046423, 2011). "The animals receiving insulin infusion developed more obesity, insulin resistance and glucose intolerance in adulthood, illustrating that short-term insulin administration during a critical period of postnatal life has serious long-term consequences for glucose regulation in rats." (PMID 21655104, 2011). "The elevated insulin levels found in MSG-obese rats can reflect insulin resistance." (PMID 21860615, 2011). "In summary, adipose tissue functions as a sink for excessive fatty acids, and the impairment of fatty acid storage function of adipose tissue results in the deposition of fatty acids in other tissues, such as key insulin responsive tissues, muscle and liver, leading to insulin resistance." (PMID 21811683, 2011). "The relationship between plasma ghrelin concentration and serum insulin level or insulin resistance in patients with type 2 diabetes is still controversial, even though a large number of studies indicated decreased plasma ghrelin levels in obese type 2 diabetic patients." (PMID 21760816, 2011). "Therefore a separate study will be needed to fully examine the interaction between insulin secretion and insulin resistance." (PMID 22164267, 2011). "Moreover insulin blunted sildenafil-induced increase in NO generation under insulin resistance conditions." (PMID 21297971, 2011). "Measures of blood pressure, insulin, triglycerides, height and insulin resistance were significantly higher (P < 0.0001) and high density lipoprotein cholesterol significantly lower (P < 0.0001) in the overweight and obese group compared to their normal weight counterparts (data not shown)." (PMID 20227263, 2011). "Defects in insulin secretion but not insulin resistance explain the susceptibility of B6.apoE-/- mice to diet-induced T2DM." (PMID 22204493, 2011). "Insulin resistance, whether acquired or genetically determined, raises serum insulin and increases serum free fatty acid (FFA) levels." (PMID 21918648, 2011).